IL6 (interleukin 6)
Diseases named in the same sentence as IL6 in open-access papers (continued):
Sharing a sentence is not in itself a finding about the gene and the disease.
Flavivirus Infections (8 papers, 2017 to 2025). Infections with viruses of the genus FLAVIVIRUS, family FLAVIVIRIDAE. "The IL-6-TF axis createsa prothrombotic state during inflammation, contributing to a dysregulatedcoagulation during severe flavivirus infections." (PMID 41322518, 2025). "Thesefindings point to a possible regulatory role of IL-6 in TF expression,establishing a link among sNS1 proteins, inflammatory signaling, andthe coagulation modulation observed during flavivirus infections." (PMID 41322518, 2025). "Future mechanistic studies on the function of IL-6 during neurotropic flavivirus infection will significantly impact the development of much-needed therapeutic interventions to improve disease outcomes." (PMID 38053527, 2023). "To further define the role of IL-6 during flavivirus infection, we planned an in vitro experiment using primary murine cells." (PMID 38053527, 2023). "Our findings in this experiment highlight the role of IL-6 in modulating the immune response to flavivirus infection in mice by differential regulation of type I interferon, cytokines, and chemokines in the periphery and brain." (PMID 38053527, 2023). "Herein, we investigated the function of IL-6 in the pathogenesis of neurotropic flavivirus infections." (PMID 38053527, 2023). "Overall, our data indicate the pivotal role of IL-6 in modulating the immune response to flavivirus infection in both human neuronal cells and mice." (PMID 38053527, 2023). "To evaluate the role of IL-6 in modulating the immune response after flavivirus infection, we measured the levels of key cytokines after IL-6 neutralization in human neuronal cells." (PMID 38053527, 2023). "Moreover, IL-6 was also downregulated, which was increased in other flavivirus infections like Zika, West Nile virus (WNV), and Japanese encephalitis virus (JEV)." (PMID 39770732, 2024). "However, the interplay between IFN-I and IL-6 during flavivirus infection is yet to be explored." (PMID 38053527, 2023). "In order to investigate the response of the respiratory epithelium upon flavivirus infection, we measured the expression levels of type I and type III IFNs and the pro-inflammatory cytokines IL-6, IL-8/CXCL8, and IP-10/CXCL10." (PMID 31057517, 2019). "Following flavivirus infection activated glial cells release TNF, IL1β, IL6, and RANTES, all of which promote bystander damage to neurons." (PMID 28873445, 2017). "However, our knowledge of the function of IL-6 during the progression of a neurotropic flavivirus infection is lacking." (PMID 38053527, 2023). "However, the effects of IL-6 on flavivirus infection have not been analyzed." (PMID 38053527, 2023).
fungal keratitis (8 papers, 2008 to 2024). "Transcriptome analysis of fungal keratitis revealed inflammatory cytokine genes, i.e., IL-1B, IL-6, TNF- α, to be significantly associated with fungal keratitis." (PMID 35328532, 2022). "Genes encoding IL-6 and IL-1β were expressed more than 300 fold during fungal keratitis." (PMID 18843377, 2008). "Former research in fungal keratitis indicated that inflammatory cytokines, IL-1β, IL-6, TNF- α, as well as Wnt, Hippo, and cGMP-PKG signaling pathways were significantly associated with the disease." (PMID 36838330, 2023). "At the advanced stages of fungal keratitis, the levels of IL-1β, IL-6, IL-8, and IFN-γ in the aqueous humor were shown to be significantly increased." (PMID 35328532, 2022). "High concentration of IL-1β, IL-6, IL-8, and IFN-γ in the aqueous humor was associated with fungal keratitis." (PMID 29673332, 2018). "The present studies demonstrate that a high concentration of IL-1β, IL-6, IL-8, and IFN-γ in the aqueous humor is associated with fungal keratitis, and the infiltrating PMN leukocytes are involved in this inflammatory response." (PMID 29673332, 2018). "At the advanced stages of fungal keratitis, the levels of IL-1β, IL-6, IL-8, and IFN-γ in the aqueous humor were significantly increased when compared with control (p<0.01)." (PMID 29673332, 2018). "Our experiment confirmed that Dectin-1 in early period of innate immune in rat fungal keratitis can work through IL-1β, IL-6, CCL2, CXCL1, CXCL2 to recruit neutrophils and macrophages to participate anti-fungal immunity." (PMID 26427623, 2015). "In the aqueous humor samples of fungal keratitis group, the levels of IL-1β, IL-6, IL-8, and IFN-γ were found to be significantly increased, as compared with the control group (P = 0.012 for IL-1β, P < 0.001 for IL-6, P < 0.001 for IL-8, and P = 0.001 for IFN-γ)." (PMID 29673332, 2018). "Dectin-1 in early period of innate immune responses in rat fungal keratitis might work through IL-1β, IL-6, CCL2, CXCL1, CXCL2 to recruit neutrophils and macrophages to participate anti-fungal immunity." (PMID 26427623, 2015). "IL-8 > IL-6 in patients with bacterial keratitis; IL-8 > IL-6 > IL-1β and increased frequency of circulating CD3−CD56+ NK cells in patients with gram-negative keratitis; and IL-8 = IL-6 > IL-1β in patients with fungal keratitis." (PMID 25741769, 2015). "Patients with fungal keratitis express IL-8, IL-6, and IL-1β in tears without changes in circulating cells." (PMID 25741769, 2015). "IL-6 measurements were as follows: 4172 ± 1873 pg/mL in fungal keratitis, 1596 ± 971 pg/mL in gram-negative bacterial keratitis, 758 ± 1166 pg/mL in gram-positive bacterial keratitis." (PMID 25741769, 2015).
gastric disease (8 papers, 2013 to 2024). "Cytokine receptors and the inflammatory cytokines IL-6 and IL-12 have a pathogenic role in gastric disease, and decreased expression levels of these indicate a preventive effect against gastric injury." (PMID 24944640, 2014). "The intestinal disease (ID) group exhibited the highest IL-6 level, which significantly differed from the stomach disease (SD) group (p < 0.05)." (PMID 38751718, 2024). "It is known that pathogenic CD4+ T cells for the transfer EAE express cytokines including IFN-γ, IL-17A, and IL-6, and very strong stress alone induces gastric disease via p38 activation at the affected tissues by the activation of the vagal pathway." (PMID 28809157, 2017). "Cytokine receptors and the inflammatory cytokines, IL-6, IL-12, TNF-α and IFN-γ, play pathogenic roles in gastric disease." (PMID 25120640, 2014). "Cytokine receptors and the inflammatory cytokines IL-6, IL-12, TNF-α and IFN-γ play a pathogenic role in gastric disease." (PMID 25187847, 2014). "Helicobacter pylori (H. pylori) induces an intense inflammatory response, mediated by proinflammatory cytokines, including interleukin (IL)-6 and its membrane receptor (IL-6R), which activates important signaling pathways in the development of gastric disease and cancer." (PMID 34008757, 2021). "Inflammatory cytokines, IL-6 and TNF-α, play a pathogenic role in diseases of the stomach." (PMID 25187847, 2014). "The inflammatory cytokines IL-6 and TNF-α play pathogenic roles in diseases of the stomach." (PMID 24137202, 2013).
geographic atrophy (8 papers, 2007 to 2024). "The pro-inflammatory cytokine IL-6 is a key mediator implicated in geographic atrophy, angiogenesis, and subretinal fibrosis." (PMID 36768783, 2023). "IL-6 has been associated with the presence of geographic atrophy secondary to AMD." (PMID 34575451, 2021). "IL-6 has been associated with the progression of geographic atrophy secondary to AMD41." (PMID 32973190, 2020). "A positive correlation between IL-6 concentration and geographic atrophy size was reported, as well as IL-8 concentration and neovascular AMD." (PMID 39062152, 2024). "Microglia, macrophages, or other cells expressing IL-6 were significantly increased in the retina of donors with geographic atrophy, suggesting the activated inflammatory activities." (PMID 33019767, 2020). "A recent meta-analysis showed that a high level of plasma interleukin-6 (IL-6) is associated with neovascular AMD and geographic atrophy, suggesting that the late stages of AMD are accompanied by chronic low-grade inflammation and the therapeutic potential of targeting systemic IL-6." (PMID 33019767, 2020). "Conversely, patients with geographic atrophy and AMD were shown to exhibit greater concentration levels of IL-6 and IL-8." (PMID 39062152, 2024). "After stimulation with A2E, no statistical differences were found in the median expression level of TNF-α, IL-6, IL-10 between the control group, and the neovascular AMD and the geographic atrophy group." (PMID 33859228, 2021). "To this end, we measured ex vivo mRNA expression of the cytokines TNF-α, IL-6, and IL-10 in whole blood samples after stimulation with A2E in a clinical sample of 27 patients with neovascular AMD and 24 patients with geographic atrophy secondary to AMD." (PMID 33859228, 2021).
gonococcal infection (8 papers, 2012 to 2024). "IL‐6 is a major pro‐inflammatory cytokine, plays an important role during gonococcal infection, and is found in the secretions of infected patients." (PMID 30697344, 2019). "This is supported by the increased levels of TNF-α and IL-6 observed in vivo in vaginal secretions of Balb/c mice after gonococcal infection." (PMID 26125939, 2015). "In Neisseria gonorrhoeae infections, there were higher protein levels of IL-6, CXCL1 and CXCL2 in the vaginal secretions of BALB/c mice." (PMID 22848503, 2012). "This suggests that DC and macrophages, which are usually located in the stroma of the genital tract of the mouse, are at least in part responsible for the increased levels of TNF-α and IL-6 observed in the vaginal secretions of Balb/c mice after gonococcal infection." (PMID 24204097, 2013). "In the murine infection model, P4 (1 mg/day) inhibited the inflammatory effects induced by gonococcal infections which led to decreased neutrophil infiltration, reduced polymorphonuclear neutrophils (PMNs) numbers, IL-1β, TNF-α, and IL-6 levels in vaginal secretions." (PMID 33633700, 2021). "In female patients attending an STI clinic in Birmingham, Alabama, aged between 17 and 57, cytokine levels in genital secretions were not higher in individuals who had gonococcal infection compared with those that did not, while the level of serum IL-6 was elevated in patients with gonorrhea." (PMID 37662926, 2023).
herpesvirus infection (8 papers, 2016 to 2025). "For example, lncRNA BX470102.1 is involved in amoebiasis, Kaposi sarcoma-associated herpesvirus infection, TNF signaling pathway, and IL-17 signaling pathway by targeting multiple target genes such as IL-6, CXCL2, and PTGS2." (PMID 36457749, 2022). "“Transferon Oral” modulates IFN-γ, TNF-α, and IL-6 and increases the survival rate in a herpes infection murine model when oropharyngeally (ORO) administered, which correlate with clinical observations where “Transferon Oral” is used as a therapeutic auxiliary in inflammatory diseases." (PMID 33117165, 2020).
hyperphosphatemia (8 papers, 2021 to 2025). Abnormally high level of phosphate in the blood. "Hyperphosphatemia exacerbates this process by activating PiT-1 receptors on monocytes, triggering IL-6 release and establishing a self-reinforcing inflammatory-calcific loop." (PMID 40959491, 2025). "In order to assess the effect of hyperphosphatemia on vascular inflammation, the pro-inflammatory cytokine IL-6 and monocyte chemoattractant protein-1 (MCP-1) were analyzed in the aortas from mice by real time PCR." (PMID 34439556, 2021). "Hyperphosphatemia activates monocytes via the phosphate transporter PiT-1, triggering TNF-α and IL-6 release to establish a pro-inflammatory microenvironment that accelerates VSMC osteogenic differentiation." (PMID 40959491, 2025). "On the other hand, we and others have shown that IL-6 by itself is not sufficient to influence HASMC calcification under hyperphosphataemia conditions." (PMID 38254629, 2023).
hypertrophic cardiomyopathy (8 papers, 2011 to 2025). A condition in which the myocardium is hypertrophied without an obvious cause. "For hypertrophic cardiomyopathy, the analysis showed a direct interaction, specifically co-expression and text mining, between IL-6 and KLF-2, KLF-4, and KLF-6." (PMID 38672763, 2024). "This is in line with several studies that reported elevated levels of circulating inflammatory markers, including tumor necrosis factor and IL-6, in hypertrophic cardiomyopathy (HCM), supporting the anti-inflammatory role of these treatments in cardiac health." (PMID 38813367, 2024). "Studies indicate elevated levels of cytokines like TNF-α, hs-CRP, and inflammatory interleukins (e.g., IL-1β, IL-1RA, IL-6, IL-10, circulating monocyte chemoattractant protein resulted in a chronic low-grade inflammatory state in hypertrophic cardiomyopathy (HCM)." (PMID 38533084, 2024). "“Hypertrophic cardiomyopathy” in the signal pathway was followed with the p.adjust value of 1.10×10-3 and the corresponding collective action gene set with mutations included 8 genes: IGF1, CACNA1S, MYH7, IL6, TTN, CACNB2, LAMA2, DMD." (PMID 37876543, 2023). "We also observed enrichment in pathways associated with circadian entrainment (e.g., GNG11, GUCY1B1) and hypertrophic cardiomyopathy (e.g., ITGB3, ITGA2B, IL6), suggesting systemic disruptions in PitNET PBMCs." (PMID 41253784, 2025). "The most significantly enriched was hypertrophic cardiomyopathy, involving 3 downregulated genes (DES, IL6, and MYL2)." (PMID 35634509, 2022).
Hypomagnesemia (8 papers, 2022 to 2025). An abnormally decreased magnesium concentration in the blood. "Hypomagnesemia correlated with increased inflammatory serum markers and cytokine levels including ferritin, IL-6, IL1Ra, IL-8, and MIP1a." (PMID 40307941, 2025). "Hypomagnesemia promotes chronic low-grade inflammation, and the levels of inflammatory cytokines (TNF-α and IL-6) are increased in Mg-deficient rodents." (PMID 34541392, 2022). "Also, hypomagnesemia enhances inflammation by promoting inflammatory genes such as TNF-α and IL-6, which suppress osteoblast function and promote osteoclast function." (PMID 38247490, 2024).
intracranial hemorrhage (8 papers, 2012 to 2025). Bleeding within the SKULL, including hemorrhages in the brain and the three membranes of MENINGES. "It is known that the risk for intracranial hemorrhage (ICH) in AVM is linked to polymorphisms in the inflammatory cytokine genes such as TNF-α and IL-6." (PMID 33648532, 2021). "Following brain hemorrhage, resident immune cells are activated and release proinflammatory cytokines and chemokines, such as tumor necrosis factor-α (TNF-α) and interleukin 6 (IL-6), inducing endothelial cells to upregulate intercellular adhesion molecule (ICAM-1)." (PMID 37899442, 2023).
lumbar disc herniation (8 papers, 2017 to 2025). "Providing evidence shows that genetic variants in the promoter regions of the IL-6 are associated with lumbar disc herniation." (PMID 30464887, 2018). "In this study, we found an association of IL-6 SNPs (rs1800796, rs1524107, rs2069840) with an increased risk of developing lumbar disc herniation." (PMID 29179499, 2017). "However, in a Han Chinese population, it was found that the relative risk of developing lumbar disc herniation with the IL-6-572 G genotype GG and CG genotypes were also high—4.48- and 1.55-fold—higher than the CC genotype." (PMID 30464887, 2018). "Higher IL-6 systemic levels in patients with lumbar disc herniation were correlated with poorer recovery, while a decrease in systemic IL-6 was correlated with improved pain in these patients." (PMID 32138314, 2020). "IL-6 is thought to have an important role in lumbar disc herniation." (PMID 30464887, 2018). "Additionally, the observed association between elevated IL-6 levels and a reduced risk of LBP may be explained by the fact that lumbar disc herniation is the most common cause of LBP." (PMID 37520547, 2023). "Our team demonstrated that PMD occurs in patients with lumbar disc herniation, which is related to the high levels of TNF-α, IL-6, and IL-1β in multifidus." (PMID 40722201, 2025). "In addition, a previous study aimed at understanding the mechanism of EA in the treatment of patients with lumbar disc herniation, which is also a neuro edema disease, and found that EA can effectively reduce the levels of IL-2, TNF-α, and IL-6 contents." (PMID 38689877, 2024).
malignant glioma (8 papers, 2006 to 2025). A grade III or grade IV glioma arising from the central nervous system. "However, in human malignant glioma cells, the levels of IL-6, IL-8, and glutamate were lower in Panx-1 siRNA transfected cells." (PMID 34475813, 2021). "In addition, IL-1β, IL-6 and IL-8 and their cognate receptors are also elevated in malignant gliomas." (PMID 22330721, 2012).
malignant mesothelioma (8 papers, 2012 to 2023). A malignant neoplasm of the pleura or peritoneum, arising from mesothelial cells. "Standard LMB‐100 infusion in patients with malignant mesothelioma caused increases in plasma IL‐6 levels 5 days after start of treatment concordant with IL‐8 increases." (PMID 36208017, 2023). "Research has shown that the activation of IL-6 signaling entirely relates to the presence of sIL-6R in malignant mesothelioma cells." (PMID 36865747, 2023). "Malignant mesothelioma (MM), a rare and aggressive tumor, is related to asbestos exposure, which mediates a chronic inflammatory process involving the cytokine IL-6." (PMID 34439164, 2021). "Other cytokines that were shown to be significantly affected in both pleural fibrosis and malignant mesotheliomas include IL-6, IL-1b, and IL-8, possibly through inflammasome activation." (PMID 26080392, 2016). "Interestingly, some of the interleukins regulated by syndecan-1 in our study, such as IL8 acts also as an autocrine growth factor whereas IL6 induces expression of VEGF in malignant mesothelioma." (PMID 23144729, 2012).
measles (8 papers, 2015 to 2025). A highly contagious viral infection caused by the measles virus. "This single-centre cohort demonstrates that an elevated admission IL-6 concentration is the clearest biochemical harbinger of impending organ dysfunction in hospitalised measles, outperforming conventional acute-phase reactants and leukocyte indices." (PMID 40872832, 2025). "Integrating IL-6-guided triage with intensified vaccination outreach could substantially reduce measles-related morbidity and health-system strain in low-coverage EU settings." (PMID 40872832, 2025). "Together, these data suggest that point-of-care IL-6 testing—already commonplace for COVID-19 triage—could be repurposed to measles, offering faster prognostication than conventional acute-phase reactants." (PMID 40872832, 2025). "Furthermore, significant associations were shown between multiple vitamin D receptors (VDR) and retinoid X receptor α (RXRA) SNPs/haplotypes and measles-specific IL-2, IL-6, IL-10, IFN-α, IFN-γ, IFNλ-1, and TNF-α cytokine secretion." (PMID 33167413, 2020). "IL-6 eclipsed CRP and procalcitonin as a severity biomarker, consistent with the cytokine’s central role in measles-induced immune dysregulation and secondary viral pneumonitis." (PMID 40872832, 2025). "Integrating IL-6-guided triage with vigilant antibiotic stewardship and accelerated MMR catch-up could, therefore, form a tripartite strategy to curb both severe measles and its downstream infectious sequelae in Romania." (PMID 40872832, 2025).